ELK1 (ETS transcription factor ELK1)
Diseases named in the same sentence as ELK1 in open-access papers (continued):
Sharing a sentence is not in itself a finding about the gene and the disease.
schizophrenia (1 paper, 2023). A major psychotic disorder characterized by abnormalities in the perception or expression of reality. "In this article, we reported that ERVWE1 amplified the expression of HTR1B, p-ERK1/2, p-ELK1, and Arc in SH-SY5Y cells and 5-HT neurons, indicating that ERVWE1 could upregulate Arc expression through the ERK cascade, thus potentially participating in the development of schizophrenia." (PMID 37990254, 2023).
serous ovarian cancers (1 paper, 2018). "Previous evidence demonstrated that KP extract significantly suppressed the phosphorylation of PI3K, AKT, ERK1/2, and Elk1 in HeLa cells, thus we hypothesized whether KP extract can suppress the activation of ERK1/2 and AKT signaling in high grade serous ovarian cancers." (PMID 29891015, 2018).
skin cancer (1 paper, 2025). "Pharmaceuticals targeting ELK1 in lung, bladder, pancreatic, renal, endometrial, and skin cancer." (PMID 40862737, 2025).
type 2 diabetes mellitus (1 paper, 2013). A type of diabetes mellitus that is characterized by insulin resistance or desensitization and increased blood glucose levels. "Indeed, three members of this subnetwork (i.e. MAPK1, INSR, SOCS3) belong to the Type II diabetes mellitus pathway, which fall into the bigger insulin signaling pathway together with SHC1 and ELK1." (PMID 23885764, 2013).
ureteral tumors (1 paper, 2018). "As for tumor site, moderate (2+) p-ELK1 expression was marginally more often (P = 0.096) seen in ureteral tumors, compared with renal pelvic tumors." (PMID 29518027, 2018). "Another possibility includes a higher proportion of muscle-invasive disease, where p-ELK1 expression is more likely stronger, in ureteral tumors (33 of 50 (66.0%)) than in renal pelvic tumors (25 of 45 (55.6%))." (PMID 29518027, 2018).
urinary bladder transitional cell carcinoma (1 paper, 2025). "The authors reported that incubation with 12-O-tetra-decanoylphorbol 13-acetate (TPA) which is a Protein kinase C (PKC) agonist, leads to profound ELK1 activation in urinary bladder transitional cell carcinoma (TCC) cell lines." (PMID 40862737, 2025). "A 2022 clinical trial investigated ELK1 among other potential biomarkers as a distinctive molecular signature of either urothelial bladder cancer (UBC) or upper tract urothelial carcinoma (UTUC)." (PMID 40862737, 2025).
uterine cancer (1 paper, 2025). Primary or metastatic malignant neoplasm involving the uterine corpus and/or the cervix. "Regarding uterine cancer, only a limited number of studies exist on ELK1 and its implications in uterine carcinomas." (PMID 40862737, 2025). "Since CIP2A has also been reported as an ELK1 target in ovarian, uterine cancer, and liver cancer, its inhibition by erlotinib provided a new mechanistic approach which could be applicable in more cancer types." (PMID 40862737, 2025).
cancer (107 papers, 2007 to 2025). A tumor composed of atypical neoplastic, often pleomorphic cells that invade other tissues. "The study revealed that cancer-associated fibroblasts (CAFs), via the excretion of glucosamine, activate ELK1, which in turn activates the transcription of the 3βHSD gene." (PMID 40862737, 2025). "ELK1-regulated noncoding RNAs in CRC have been implicated in multiple cancer hallmarks, including EMT, TME remodeling, and metabolic adaptation." (PMID 40862737, 2025). "The relationship between the ETS family and lncRNAs has been proven by several studies, and it has been reported that ELK-1 induces the upregulation of lncRNAs and is associated with the growth of cancer cells." (PMID 36612299, 2023). "Further analysis of these differential sites revealed the increased enrichment of motifs for other ETS TFs such as FLI1, ELK4 and ELK1, which have been implicated in cancer progression, following TWEAK-induced p52 activation." (PMID 37087499, 2023). "Considering the unique role of ELK1 in activating gene transcription associated with cancer progression, its value as a prognostic marker deserves in-depth evaluation." (PMID 34966781, 2021). "Univariate analysis revealed that p-ELK1 overexpression was also marginally and significantly associated with disease progression and cancer-specific mortality, respectively, in patients with UUTUC." (PMID 29518027, 2018). "Mechanistically, MBZ can modulate the cancer-associated pathways including ELK1/SRF, AP1, STAT1/2, MYC/MAX, although the regulatory outcomes are context-dependent." (PMID 28099902, 2017). "By using a panel of previously well-characterized cancer-associated pathway reporter analyses, we found at least four pathways, e.g., ELK1/SRF, AP1, STAT1/2, MYC/MAX, are significantly affected." (PMID 28099902, 2017). "An increase in Elk-1 phosphorylation can cause increased nuclear translocation, which leads to cancer progression." (PMID 27542222, 2016). "We analyzed the effect of monensin on 11 cancer-associated pathways and found that monensin inhibits the reporter activities for the Elk1/SRF, AP1, NFκB and STAT pathways, and to a lesser extent the Myc/Max reporter activity." (PMID 26639992, 2015). "Hence, the purpose of this study is to focus on ELK1, a TF which has repeatedly been reported in numerous cancer-associated phenomena, and review existing literature regarding the protein’s role." (PMID 40862737, 2025). "In regard to cancer, the phosphorylation of this threonine residue in ELK1 is associated with a number of malignancies, including colonic adenocarcinomas where Thr-417 phosphorylation is significantly elevated in this carcinoma compared to normal colonic epithelium." (PMID 35281802, 2022). "In addition, the genes significantly associated to OS were enriched for targets of several key cancer TFs like ELK1, YY1 and RUNX3." (PMID 36584096, 2022). "Mechanistically, MBZ can modulate several cancer-associated pathways, such as ELK1/SRF, AP1, STAT1/2, MYC/MAX, although the regulatory outcomes may be context-dependent." (PMID 28099902, 2017). "Furthermore, recent influential studies have shown that the activation of RAS/RAF/MEK/ERK signaling modulates the expression of Snail via MSK1/Elk-1-mediated epigenetic regulation, and thus promotes cell motility and invasive behavior in cancer-associated EMT." (PMID 25797261, 2015). "However, given the fact that ELK1 has been found implicated in both paclitaxel and cisplatin/oxaliplatin resistance, these mechanisms may be tissue/cancer-specific." (PMID 40862737, 2025). "The study revealed that the transcription of EZH2 is ELK1-dependent, and that EZH2’s overexpression is associated with aggressive cancer types like TNBC and EGFR-overexpressing BC." (PMID 40862737, 2025). "The correlation between ELK1 activation and growth factors is one of the earliest regarding ELK1’s role in cancer." (PMID 40862737, 2025).
cancer (continued). "According to most data, ELK1 is simultaneously implicated in several functions, acting as a main downstream target of ERK1/2, which are two of the most significant kinases in cancer biology and epicenter of several anticancer approaches." (PMID 40862737, 2025). "Over the years, a significant number of studies on ELK1 in liver (or hepatic) cancer have been conducted." (PMID 40862737, 2025). "The role of ELK1 in cancer cell aggressiveness was also validated by another study focusing on Octamer transcription factor 1 (OCT1; also known as POU domain, class 2, transcription factor 1, POU2F1)." (PMID 40862737, 2025). "It is noteworthy that the observed outcome of ELK1’s activation is a combination of its upstream regulation and the tissue- or cancer-specific expressed/activated transcription factors which collaborate with ELK1 to facilitate transcription." (PMID 40862737, 2025). "In the MAPK/Ras pathways, nine proteins were downregulated including C-Raf_pS338, MAPK_pT202_Y204, Elk1_pS383, Tau, Creb, C-Myc, JNK_pT183_Y185, c-jun_pS73, and Ets_1, while three proteins were upregulated in cancer including B-Raf_pS445, MNK1, and PAK1." (PMID 41284888, 2025). "MYC is overregulated in three of the five datasets and is related to: 1) cellular senescence along with FOXM1; 2) proteoglycans in cancer along with ELK1; and 3) HCV infection." (PMID 39228892, 2024). "A notable example is the activity of the MAPK/ERK/ELK1 signaling pathway, which was distinguished in survival, cancer stemness, and the immune microenvironment." (PMID 39678513, 2024). "Elk1 genetic ablation in cancer epithelial cells suppressed CAF-induced androgen biosynthesis in vivo." (PMID 37009898, 2023). "CAF production of glucosamine increases GlcNAcylation in cancer cells, promoting Elk1-induced HSD3B1 transcription." (PMID 37009898, 2023). "CAFs induced higher GlcNAcylation in cancer cells and elevated expression of the transcription factor Elk1, which induced higher 3βHSD1 expression and activity." (PMID 37009898, 2023). "Once activated, ERK1/2 is transferred to the nucleus where it regulates the activity of various transcription factors (such as Elk1, c-Fos, c-Jun, and c-Myc) through phosphorylation, thereby contributing to tumorigenesis or cancer growth." (PMID 36613552, 2022). "The MAPK pathway is effectively involved in the regulation of cancer cell proliferation, invasion and survival by activating target genes such as transcriptional factor ELK1, C-Fos and the ErbB, VEGF, which contributes to the progression of tumors." (PMID 36352482, 2022). "In silico analysis of the sequence showed high homology to the ETS domain-containing protein-1 (ELK1)-binding sequence which is involved in cell growth, differentiation, angiogenesis, and cancer." (PMID 35892692, 2022). "A growing number of studies have confirmed that ELK1 is the downstream target of miRNAs, including miRNA-135a, miRNA-873 and miR-185-5p, in diverse cancers." (PMID 35123530, 2022). "The overexpression of elk1 in macrophages significantly inhibited the phagocytosis of macrophages on cancer cells." (PMID 35911773, 2022). "ELK1 contributes to the inhibition of miR-134 expression in human cancer, which was largely consistent with our findings." (PMID 33621196, 2021). "In short, the transcription factor ELK1 exerts a cancer-promoting effect by binding to the B7-H3 promoter region and stimulating its transcriptional activity, especially promoting EMT." (PMID 34970415, 2021). "Studies reported that CXCL5 induced the EMT process in cancer cells by activating ERK/Elk-1/Snail, AKT/GSK3β/β-catenin, or ERK/Snail signaling pathways." (PMID 34603292, 2021). "Overexpression of ELK1 is known to promote apoptosis in neurons, but apoptosis in most cancer cells is reduced by ELK1 overexpression." (PMID 34572320, 2021). "ELK1 is a transcription factor binding to purine‐rich DNA sequences and has been shown to be up‐regulated in various cancers." (PMID 32715641, 2020).
cancer (continued). "The mRNA and protein levels of macrophage ELK-1 and SIRPα in carcinoma tissue samples were much higher than those in adjacent normal tissue samples." (PMID 32296015, 2020). "Transcription factors important in cancer and proinflammation pathways such as NFkB, Elk-1, C/EBPβ, or AP-1 are activated by both IL-1 ligands and EGF." (PMID 31320902, 2019). "Elk-1 regulates migration of multiple cancer types through its downstream targets including c-fos, EGR1, and PKCα." (PMID 29765550, 2018). "Further to test the role of ELK1 in regulating of ZNF598 level, we knocked down ELK1 expression using shRNAs in different types of cancer cell." (PMID 29464043, 2018). "MAPK/ERK pathway regulates cancer cell growth, differentiation and survival by phosphorylating downstream substrates such as Elk-1, c-Myc, c-Fos, c-Jun, ATF, NF-κB and AP-1." (PMID 29383165, 2017). "Only ELK1, a TF downstream of the MAPK/ERK pathway, is dysregulated by PIK3CA or PTEN mutations in all three cancers." (PMID 28139702, 2017). "NDUFA4L2 was involved in multiple cancer-related growth and survival pathways and its expression level was positively correlated with ELK1 in ccRCC tissues." (PMID 29158991, 2017). "Another important node of MAP kinase mediated anti-cancer cascade is the ETS domain transactivation factor Elk1 whose phosphorylation at serine 383 by MAP kinases triggers apoptotic induction and growth inhibition." (PMID 29263422, 2017). "In particular, in cancer cells Elk-1 has been shown to correlate with tumor progression via activation of different genes that regulate cell growth, differentiation, and survival." (PMID 26824320, 2016). "The inhibitory effects of MZF-160–72 on tumorigenesis further demonstrated that this region of MZF-1 is essential for the formation of the MZF-1/Elk-1 interaction and transcriptional activation of PKCα which is highly expressed in cancer cells." (PMID 27542222, 2016). "BRP negatively regulated the expression of numerous genes involved in the development of several types of cancer such as: fos, elk1, Pik3ca, Prkca." (PMID 26660901, 2015). "Using a quantitative RT-PCR method, we then assessed the effects of ELK1 silencing on the expression of MMPs that are known to play a critical role in cancer cell migration/invasion, angiogenesis, and resultant tumor progression and metastasis." (PMID 26342199, 2015). "The involvement of ELK1 signals in cancer development, possibly via the regulation of inflammatory responses, has also been documented." (PMID 26342199, 2015). "Altough the correlation between Elk-1 and cancer progression has been strengthened, we examined the role of Elk-1 in EMT for the first time in this study." (PMID 25326651, 2014). "By regulating the genes, such as plasminogen activator-1 and metalloproteinases-2 and -9, Elk-1 plays a crucial role in cancer progression." (PMID 25326651, 2014). "In accordance with our results, Elk-1-dependent regulation of Mcl-1 expression has been described with other types of cancer." (PMID 23158473, 2012). "These cancer-associated target mRNAs were connected to this network mainly through the interaction with apoptosis and cell death genes such as BCL2, CASP9 and ELK1." (PMID 21595958, 2011). "ELK1 has also been reported to participate in cancer chemoprevention." (PMID 40862737, 2025). "ELK1 as an independent prognostic factor has been suggested by numerous researchers, highlighting the protein’s role in tumorigenesis-related processes and its correlation to aggressive form of cancer." (PMID 40862737, 2025). "Phosphorylated ELK1 synergizes with other TFs to facilitate transcription, and these complexes are of increased significance in tumorigenesis and tumor growth in several cancer types." (PMID 40862737, 2025). "The authors concluded that ELK1 expression is indeed different between the two cancer subtypes." (PMID 40862737, 2025). "Targeting ELK1’s activation has been reported to be a cancer-preventative strategy." (PMID 40862737, 2025).
cancer (continued). "Targeting the recruitment of these complexes on gene promoters may be a promising therapy in several cancer types, since upon activation, ELK1 promotes the expression of several oncogenes including EGR1 and FOS." (PMID 40862737, 2025). "A major part of this concept could be the exploitation of naturally evolved ELK1 regulation mechanisms which also regulate other TFs and could be weaponized against cancer." (PMID 40862737, 2025). "Moreover, ELK1 has been identified as a molecular target of miR-217, which can exhibit tumor-suppressing activity in various cancers." (PMID 40862737, 2025). "ELK1 has been shown to mainly play an oncogenic role in various types of cancer." (PMID 38397056, 2024). "Furthermore, by suppressing the expression of the MAPK signaling pathway-activated ETS domain-containing protein Elk-1 (ELK1), miR-326 prevents the growth of cancer cells." (PMID 38317930, 2024). "Furthermore, ELK1 has been involved in chemoresistance, including cisplatin and gemcitabine, in different types of cancer." (PMID 38397056, 2024). "To determine whether Elk1 regulates cancer cell growth, we conducted in vitro and mouse xenograft studies with control LNCaP and ELK1-KO cells." (PMID 37009898, 2023). "Elk1 is reported to have roles in cancer development, including cell proliferation, the cell cycle, apoptosis, and tumorigenesis, although its role in DLBCL remains unclear." (PMID 36897912, 2023). "It is noteworthy, that some of the transcription factors which have been previously linked to EZH2 activation, albeit in other cancer entities, underlie transcriptional control by NFATc1 (MYC, STAT3) or represent well-characterized NFATc1 partner proteins (STAT3, ELK1)." (PMID 34943970, 2021). "ELK1 plays a crucial role in the development of human cancers." (PMID 34455918, 2021). "Overexpression of ELK1 further increased cancer cells proliferation, invasion and survival." (PMID 34966781, 2021). "In cancer, ELK1 was confirmed to affect tumor cell proliferation and apoptosis." (PMID 34970415, 2021). "In this study, we report that ELK1, as the transcriptional regulator of B7 homolog 3 (B7-H3; CD276), causes the latter to be upregulated in LUAD and further promotes malignant biological behaviors in cancer cells, in particular EMT." (PMID 34970415, 2021). "Lactate, which is highly produced by a vast number of cancers, might induce Ap-2α activity and subsequently promote Elk-1 and Sirpα expression in TAMs." (PMID 32296015, 2020). "The literature on the involvement of ELK1 in cancers is burgeoning." (PMID 32670874, 2020). "In order to test whether hsa_circRPPH1_015 exerts cancer-promoting effect via regulation of ELK1, a target gene of miR-326, cell proliferation, invasion, and cell cycle distribution were examined by EdU, Transwell, and flow cytometry, respectively." (PMID 32670874, 2020). "One of 2 TFs, ELK1, is an important regulator and known to activate many lncRNAs including TRPM2‐AS, MIR100HG, and HOXA10‐AS in cancer until now, indicating ELK1 may induce expression of LINC01234 to promote tumor progression in GC too." (PMID 32011780, 2020). "In human CRC patient samples, we confirmed that the Elk-1 protein could bind to the Sirpα DNA promoter in TAMs and that carcinomas could potentiate this effect." (PMID 32296015, 2020). "However, a pile of data show that both SAF/MAZ and Elk-1 play central role in inflammation and cancer pathogenesis." (PMID 30610159, 2019). "Whether transcription factors mediating oncogenic programs in cancer cells, such as ELK1 downstream of the RAS/MAPK cascade, are responsible for KMT2C recruitment onto promoter regions is a hypothesis that warrants further investigation." (PMID 30665945, 2019). "Kaplan-Meier and log-rank tests revealed that patients with phospho-ELK1(2+) tumor had marginally and significantly higher risks of disease progression (P = 0.055) and cancer-specific mortality (P = 0.008), respectively, compared to those with phospho-ELK1(0/1+) tumor." (PMID 29518027, 2018).